SP1 (Sp1 transcription factor)
Diseases named in the same sentence as SP1 in open-access papers (continued):
Sharing a sentence is not in itself a finding about the gene and the disease.
mesothelioma (5 papers, 2012 to 2023). A usually malignant and aggressive neoplasm of the mesothelium which is often associated with exposure to asbestos. "Specifically, Qc has been shown to interact with Sp1 in pull-down experiments in mesothelioma cells in vitro, preventing the interaction with the binding sites on target gene promoters." (PMID 37627542, 2023). "Because SP1 regulates the basal activity of the tyms promoter we studied the SP1-responsive regions on the tyms promoter in mesothelioma cells." (PMID 37894370, 2023). "Cafestol and kahweol modulated the promoter activity and protein expression level of the Sp1 regulatory genes including Cyclin D1, Mcl-1, and Survivin in mesothelioma cells." (PMID 22734486, 2012). "However, the variation of Sp1 levels between the lowest and the highest expressing mesothelioma cell line investigated was 4-fold." (PMID 26848772, 2016). "In this study, we focused on whether cafestol and kahweol suppressed mesothelioma cell growth (MSTO-211H and H28) and whether cafestol and kahweol can inhibit the expression of transcription factor Sp1 and induce apoptotic cell death in MSTO-211H cells." (PMID 22734486, 2012). "Because we did not detect any changes in the SP1 expression in response to EPE, we decided to check its localization in EPE-treated mesothelioma cells." (PMID 37894370, 2023).
myeloid leukemia (5 papers, 2013 to 2019). A clonal proliferation of myeloid cells and their precursors in the bone marrow, peripheral blood, and spleen. "Molecular investigations of myeloid leukemia cell lines revealed the presence of binding sites for ubiquitous (NF-1 and SP-1) and myeloid enriched (MZF-1-like protein, GATA-1, and Ets-1) transcription factors in the promoter region of the gene." (PMID 31709175, 2019). "It is also reported that miR-29b can interact with Sp1 to form the Sp1/NFκB/HDAC/miR-29b regulatory network in myeloid leukemia." (PMID 23894614, 2013). "Recently, another study revealed that METTL3 binds to the promoter region of SP1 with the aid of transcription factor CEBPZ, which enhances m6A modification of SP1, strengthens SP1 gene expression, and ultimately leads to myeloid leukaemia." (PMID 30031372, 2018). "A previous study demonstrated that RELA could form a complex with SP1 and bind to the promoter region of KIT in myeloid leukemia cells." (PMID 31363162, 2019).
pancreatic adenocarcinoma (5 papers, 2015 to 2024). "Conclusively, the present study elucidated a key regulatory loop AK4P1/miR-375/SP1 in pancreatic adenocarcinoma." (PMID 36476264, 2023). "Further analysis showed that SP1 was a potential downstream target gene of miR-375 in pancreatic adenocarcinoma." (PMID 36476264, 2023). "Intriguingly, AK4P1 expression was significantly decreased after knockdown of SP1 in pancreatic adenocarcinoma." (PMID 36476264, 2023). "Using the GSE15471 and TCGA-Pancreatic adenocarcinoma (PAAD) datasets, we analyzed the clinical importance of TOP2A-associated genes (HDAC1, HDAC2, HMGB1, HMGB2, NFYA, NFYB, NFYC, and SP1)." (PMID 32977589, 2020). "However, in clinical studies, the authors did not confirm the significant interdependence of overexpressed SP1 status with lymph node metastasis and progressive invasion in pancreatic adenocarcinoma patients." (PMID 37894370, 2023). "Intriguingly, expression determination validated that SP1 could positively regulate AK4P1 levels in pancreatic adenocarcinoma." (PMID 36476264, 2023). "Among these target genes, only SP1 expression could be negatively regulated by miR-375 in pancreatic adenocarcinoma." (PMID 36476264, 2023). "Finally, a key regulatory loop AK4P1/miR-375/SP1 was identified in pancreatic adenocarcinoma." (PMID 36476264, 2023). "Our findings suggested that AK4P1 increased SP1 expression by competitively binding to shared miR-375 and SP1 could conversely positively regulate AK4P1 expression in pancreatic adenocarcinoma." (PMID 36476264, 2023).
pneumonia (5 papers, 2014 to 2021). An acute, acute and chronic, or chronic inflammation focally or diffusely affecting the lung parenchyma, caused by an infection in one or both of the lungs (by bacteria, viruses, fungi, or mycoplasma.). "Our study gave a particular focus to Sp1, a serotype famous for its high attack rate and ability to cause a wide range of invasive disease (pneumonia, empyema, meningitis) as well as outbreaks in small/closed communities." (PMID 26214695, 2015). "There are currently licensed vaccines against various serotypes of S. pneumonia (i.e., Prevnar 13, which includes Sp1) yet the structure/immunogenicity ratio is still not entirely known." (PMID 34579258, 2021).
psoriasis (5 papers, 2013 to 2025). An autoimmune condition characterized by red, well-delineated plaques with silvery scales that are usually on the extensor surfaces and scalp. "Little information is available about the involvement of Sp1 in psoriasis." (PMID 36139479, 2022).
renal carcinoma (5 papers, 2016 to 2023). A carcinoma arising from the epithelium of the renal parenchyma or the renal pelvis. "It was demonstrated that melatonin induces the expression of transcription factors of Sp1 and E2F1, coinciding with the induction of BimEL in renal cancer Caki cells." (PMID 30388852, 2018).
rheumatoid arthritis (5 papers, 2014 to 2022). A chronic, systemic autoimmune disorder characterized by inflammation in the synovial membranes and articular surfaces. "In unpublished studies, antibodies to Sp1 and CA6 were found in less than 5 percent of normal controls and patients with rheumatoid arthritis lacking secondary SS." (PMID 24885364, 2014).
sarcoma (5 papers, 2016 to 2022). A usually aggressive malignant neoplasm of the soft tissue or bone. "SIN3 transcription regulator family member A (SIN3A) and SP1 were suggested to be highly expressed in sarcoma." (PMID 35590288, 2022). "To inhibit the activity of SP1 and other SP family members in sarcoma TICs we have used a newly developed mithralog which shows a potent anti-tumor activity while being less toxic than MTM and other mithralogs." (PMID 27105533, 2016). "We found that SP1-mediated transcription was among the most significantly altered signaling and that the inhibition of SP1 expression and activity by EC-8042 efficiently inhibited the in vitro and in vivo growth in these models of sarcoma initiating cells." (PMID 27105533, 2016). "Among the SP1 downstream targets, that we found to be efficiently downregulated by MTM, there are some of the genes most commonly amplified/upregulated in sarcomas, such as C-MYC, VEGF or IGF1R." (PMID 33806182, 2021). "Indeed, we found that the treatment of sarcoma cells with both free and encapsulated MTM resulted in the inhibition of a wide array of SP1 downstream targets." (PMID 34488783, 2021). "Earlier studies have demonstrated SP1 overexpression in various cancers including sarcoma, and adenocarcinomas in colon or stomach, whereas minimal or no expression of SP1 was detected in normal differentiated cells." (PMID 30976063, 2019). "In this line, several members of the SP family of TFs, such as SP1, SP3 and SP4, have been found to play an important role in the pathogenesis of some cancers including sarcomas and may constitute relevant therapeutic targets." (PMID 27105533, 2016).
acute kidney injury (4 papers, 2019 to 2025). Sudden and sustained deterioration of the kidney function characterized by decreased glomerular filtration rate, increased serum creatinine or oliguria. "It's demonstrated that Sp1 can activate Klotho in renal tubular epithelial cells, and overexpression of SP1 will alleviate fibrosis in HK-2 by enhancer Klotho expression, as well as alleviate acute kidney injury." (PMID 40034749, 2025). "Whether the overexpression of SP1 can activate autophagy through miR-205/PTEN/Akt signaling pathway to alleviate acute kidney injury caused by I/R has not been reported yet." (PMID 33546692, 2021). "There were also reliable weak and moderate correlations between renal failure and dityrosine concentration (r = 0.27, r = 0.45, r = 0.39, r = 0.36, and r = 0.46 in samples ADP–saline, ADP1, ADP2, SP1 and SP-saline, respectively, p = 0.045)." (PMID 31126140, 2019). "In summary, we found that overexpression of SP1 overexpression could restore autophagy through miR-205/PTEN/Akt pathway and repair the damage- re-implantation- induced acute kidney injury." (PMID 33546692, 2021).
clear cell renal cell carcinoma (4 papers, 2020 to 2025). "NNMT induces cellular invasion via activating PI3K/Akt/SP1/MMP-2 pathway in clear cell renal cell carcinoma (ccRCC)." (PMID 36817086, 2023).
dry eye (4 papers, 2015 to 2021). "The higher prevalence of anti-SP1 was also reported in the SS group and in idiopathic dry eye patients of the of the Dry Eye Assessment and Management (DREAM) cohort." (PMID 34249010, 2021). "In patients with only dry eyes, equal numbers of patients express either anti-SP1, anti-CA6 or anti-PSP with several patients expressing two or all three of these autoantibodies." (PMID 28270126, 2017). "In patients with dry eyes and dry mouth and Schirmer’s tests 3 mm < SCH < 6 mm, anti-SP1 was the dominant autoantibody while in the patients with Schirmer’s tests < 3 mm, anti-CA6 was the dominant autoantibody." (PMID 28270126, 2017). "The current studies were established to investigate the presence of anti-SP1, anti-CA6 and anti-PSP in a population of patients with dry eyes." (PMID 28270126, 2017). "A recently published report on these novel autoantibodies in participants of the DREAM Study demonstrated a higher prevalence of anti-SP1 in patients with SS-related dry eye compared to patients with non-SS dry eye (33% vs. 19%)." (PMID 30766890, 2019). "Antibodies to SP1, CA6 and PSP occur in some patients with idiopathic dry eyes." (PMID 28270126, 2017). "Patients with disease for less than 2 years and mild dry eyes did not express anti-Ro or anti-La, while 25% expressed anti-SP1." (PMID 28270126, 2017). "Interestingly, the University of Pennsylvania SICCA cohort study indicated anti-SP1 IgM and anti-PSP IgA as most prevalent, instead of anti-CA6, in SS-dry eye compared to non-SS dry eye." (PMID 34249010, 2021).
emphysema (4 papers, 2007 to 2025). "Our data suggest that the capsule type has less importance in enhancing smoke-induced emphysema as the two strains with the 106.66 backbone (Sp1 and Sp3) tended to have higher Lm values regardless of capsule type." (PMID 33295863, 2020).
Ewing sarcoma (4 papers, 2018 to 2025). A small round cell tumor that lacks morphologic, immunohistochemical, and electron microscopic evidence of neuroectodermal differentiation. "It has always been referred to as an SP1 inhibitor with other data suggesting activity against ETS transcription factors and EWS‐FLI1, the oncogenic driver of Ewing sarcoma." (PMID 33332735, 2021).
gallbladder cancer (4 papers, 2017 to 2022). "A recent study reported that upregulation of LINC00152 by the SP1 transcription factor promotes gallbladder cancer cell growth and tumor metastasis by affecting the PI3K/AKT pathway." (PMID 28220683, 2017). "LINC00152 is significantly upregulated in gallbladder cancer, and the upregulation of LINC00152 by SP1 promotes gallbladder cancer cell growth and tumor metastasis by targeting the PI3K/AKT signaling pathway." (PMID 36033524, 2022).
glaucoma (4 papers, 2009 to 2022). Increased pressure in the eyeball due to obstruction of the outflow of aqueous humor. "Future studies will explore the possibility of regulating the SP1/ANGPTL7/ROCK axis as targeted therapies for steroid-induced glaucoma and POAG." (PMID 35136015, 2022). "FBLN1 was recently discovered as a downstream target of SP1 transcription factor (SP1) in a manuscript regarding the network analysis of human glaucoma." (PMID 21655357, 2011). "Our analysis of glaucomatous astrocytes indicated that the synergistic activation of the major hubs SP-1, VDR, NF-κB and AP-1 in response to oxidative stress and mild ischemia associated with glaucoma, orchestrates genome-wide changes in the transcriptional profile and chronic activation of ONHAs." (PMID 19426536, 2009). "A previous study reported that transcription factor specificity protein 1 (SP1) is involved in promoter activity and further regulates the F-actin architecture of the Schlemm’s canal endothelium, suggesting that SP1 may function in the development and progression of glaucoma." (PMID 35136015, 2022). "This study shows that ANGPTL7 transcriptionally regulated by SP1 can modulate CLAN formation via the RhoA/ROCK pathway and provides novel insights into how the TM ultrastructure and functions may be altered in some types of glaucoma." (PMID 35136015, 2022).
iron deficiency (4 papers, 2007 to 2024). "The protein level of HIF1α was found to be elevated in cases of iron deficiency, while the protein level of Sp1 remained unchanged; however, the phosphorylation level of Sp1 showed an increase." (PMID 39228402, 2024). "The findings indicated that iron deficiency specifically upregulated the transcriptional activity of HIF1α and Sp1 on SPNS2, with Sp1 demonstrating a more pronounced increase in transcriptional activity compared to HIF1α." (PMID 39228402, 2024). "In summary, utilizing a unique GeneChip® dataset and a variety of computational approaches has allowed us to predict that some genes important for the response to iron-deficiency in the rodent intestine are transcriptionally regulated by SP1 or a related TF." (PMID 18005439, 2007). "Moreover, Sp1 itself binds ATP7A promoter in human intestinal epithelial cells being fundamental for the HIF2α-mediated induction of gene transcription during iron deficiency/hypoxia to regulate iron balance." (PMID 30530920, 2018). "SP1 and c-myc were down-regulated in embryonic tissue in response to maternal iron deficiency." (PMID 23110188, 2012). "SP1 or a closely related factor may play a primary role in the genetic response to iron-deficiency in the mammalian intestine." (PMID 18005439, 2007). "Our data thus suggests that SP1 or a related TF could be involved in regulating some of the genes in the 228 up-regulated cluster during iron-deficiency." (PMID 18005439, 2007). "Our observations thus indicate that SP1 or a related factor may be involved in regulating a subset of genes in the 228 up-regulated cluster during iron-deficiency." (PMID 18005439, 2007). "Treatment with PX478, an inhibitor of HIF1α, and Mithramycin A, an inhibitor of Sp1, resulted in a reversal of the upregulation of SPNS2 mRNA and protein expression caused by iron deficiency, with Mithramycin A exhibiting a more pronounced effect." (PMID 39228402, 2024). "Three SP1 PWMs, V$SP1_Q2_01, V$SP1_Q4_01 and V$SP1_Q6, were significant in the previous analyses at the binding site and gene levels, so we utilized these matrices to search for other TFs that may work in conjunction with an SP1-like factor to regulate intestinal genes during iron-deficiency." (PMID 18005439, 2007).
laryngeal carcinoma (4 papers, 2016 to 2023). Carcinoma that arises from the laryngeal epithelium. "We focused on Sp1 as it plays a crucial role in the transcription of genes lacking a canonical TATA box, such as the present one; in fact, Sp1 has been reported to bind to this promoter, influencing miR-27a expression in breast and laryngeal cancer cells." (PMID 37627542, 2023). "We conclude that demethylated SP1 sites in miR-23a-27a-24-2 cluster upregulate the cluster expression, leading to proliferation promotion and early apoptosis inhibition in laryngeal cancer cells." (PMID 27099864, 2016). "Moreover, MYCT1 has also been reported to inhibit EMT and the migration of laryngeal cancer cells via the SP1/miR-629-3p/ESRP2 pathway." (PMID 37587470, 2023). "We conclude that demethylated SP1 sites in CG-rich region of miR-23a-27a-24-2 cluster promoter result in the cluster overexpression, leading to proliferation promotion and apoptosis inhibition probably via targeting the related targets such as APAF-1 and PLK2 in laryngeal cancer cells." (PMID 27099864, 2016).
liver disease (4 papers, 2016 to 2024). "The most commonly reported splice variant, Sp1, produces a novel pol protein termed the hepatitis B spliced protein, which is involved in cellular apoptosis and liver disease progression." (PMID 38501924, 2024). "Sp1 hepatitis B splice protein contributes to liver disease progression and apoptosis; however, the function of other HBV splice variant novel fusion proteins remains largely unknown." (PMID 38501924, 2024).
malignant pleural mesothelioma (4 papers, 2012 to 2024). A malignant neoplasm that arises from mesothelial cells in the pleura and shows a diffuse growth pattern. "Resveratrol effectively inhibits tumor growth by inhibiting Sp1 expression and inducing apoptotic cell death, and Sp1 becomes a novel molecular target for resveratrol in human malignant pleural mesothelioma." (PMID 29850614, 2018).
Myocardial fibrosis (4 papers, 2021 to 2024). "SP1 is crucial for AngII-induced myocardial fibrosis and inflammation, with cardiac fibrosis being mediated through the SP1/TGF-beta/Smad3 signaling pathway and inflammation via the SP1/NF-κB/miR-29 signaling pathway." (PMID 39062521, 2024). "Exploring additional regulatory pathways for SP1-mediated apoptosis, myocardial fibrosis, vascular calcification, and other pathological processes, as well as identifying other target genes, is crucial for a comprehensive study." (PMID 39062521, 2024). "When rats were treated with AG-14361 or infecting rats with Sp1 shRNA, myocardial fibrosis was attenuated." (PMID 34124031, 2021). "Furthermore, SP1 is involved in the regulation of diabetic cardiomyopathy and myocardial fibrosis by affecting autophagy, apoptosis, oxidative stress, and EndMT." (PMID 39062521, 2024). "Mechanistically, SJ-12 lowered the Sp1 O-GlcNAcylation through blocking OGT to stabilize SERCA2a, mitigating myocardial fibrosis and hypertrophy." (PMID 39252788, 2024). "However, using BEZ235 or infecting rats with Sp1 shRNA and AD-PARP1 adenovirus aggravated myocardial fibrosis." (PMID 34124031, 2021).
promyelocytic leukemia (4 papers, 2013 to 2024). "Arsenic induced ROS-generation was reported to oxidize Sp1 to affect gene expression in promyelocytic leukemia cells." (PMID 23626778, 2013). "There is also evidence for ATF7IP2 and ATRX transcriptional activation role, through SP1 and DAXX interaction, in promyelocytic leukemia nuclear bodies." (PMID 28293299, 2017). "To validate this finding, we performed EMSA with nuclear extracts from HL60 cells (human promyelocytic leukemia cells) in the presence or absence of a non-biotin-labeled SP1 competitor and antibodies specific for SP1." (PMID 24940746, 2014).
squamous cell carcinoma (4 papers, 2011 to 2025). A carcinoma arising from squamous epithelial cells. "It was shown that incubation of human epidermoid carcinoma cells with PMA for more than 3 h leads to the deacetylation of Sp1 transcription factor." (PMID 30634395, 2019). "Furthermore, consistent with the experimental results, we also found that SP1 was indeed expressed at lower levels in adenocarcinoma (ADC) than in squamous cell carcinoma (SCC) from the TCGA." (PMID 40258813, 2025). "Squamous cell carcinomas might regulate cathepsin B expression through transcription factors Ets1, Sp1, and Sp335, ultimately leading to immune resistance and tumor progression." (PMID 37805623, 2023).
aortic aneurysm (3 papers, 2016 to 2024). A ruptured aneurysm located in the wall of the proximal portion of the descending aorta proceeding from the arch of the aorta. "Also, SP1 can regulate the expression ofNF-κB related cytokines, and is associated with inflammation in aortic aneurysm andheart failure." (PMID 27737314, 2016). "Additionally, SP1 plays a role in clinical vascular diseases like aortic aneurysm, aortic dissection, and pulmonary hypertension." (PMID 39062521, 2024).